KPNA6 (karyopherin subunit alpha 6)
Description:
Functions in nuclear protein import as an adapter protein for nuclear receptor KPNB1. Binds specifically and directly to substrates containing either a simple or bipartite NLS motif. Docking of the importin/substrate complex to the nuclear pore complex (NPC) is mediated by KPNB1 through binding to nucleoporin FxFG repeats and the complex is subsequently translocated through the pore by an energy requiring, Ran-dependent mechanism. At the nucleoplasmic side of the NPC, Ran binds to importin-beta and the three components separate and importin-alpha and -beta are re-exported from the nucleus to the cytoplasm where GTP hydrolysis releases Ran from importin. The directionality of nuclear import is thought to be conferred by an asymmetric distribution of the GTP- and GDP-bound forms of Ran between the cytoplasm and nucleus.
Synonyms: IPOA7; KPNA7; MGC17918; FLJ11249
Tractability: PROTAC: ubiquitination databases record sites on it; its protein half-life has been measured.
Gene: Protein-coding gene on chromosome 1 (32,108,056 to 32,176,563, forward strand). Ensembl gene ENSG00000025800.
Subcellular location (Human Protein Atlas): Cytosol; Nucleoplasm
Pathways (Reactome):
DNA Replication: Assembly of the ORC complex at the origin of replication
Gene Ontology:
Molecular function: protein binding; nuclear import signal receptor activity
Biological process: entry of viral genome into host nucleus through nuclear pore complex via importin; positive regulation of viral life cycle; NLS-bearing protein import into nucleus; protein import into nucleus
Cellular component: membrane; NLS-dependent protein nuclear import complex; cytosol; nucleoplasm; cytoplasm; host cell
Genetic constraint (gnomAD): Loss-of-function variants: 8 observed, 59.94 expected, observed/expected ratio (o/e) 0.13, 90% interval 0.077 to 0.24. The upper end of that interval is the gene's LOEUF score, 0.24, which puts it in group 1 of 6, group 1 being the genes least tolerant of losing a copy. Missense variants: 324 observed, 612.97 expected, observed/expected ratio (o/e) 0.53, 90% interval 0.48 to 0.58. Synonymous variants: 197 observed, 230.08 expected, observed/expected ratio (o/e) 0.86, 90% interval 0.76 to 0.96.
Homologues: Orthologues: dog KPNA6 (99% identical), macaque KPNA6 (99% identical), rabbit KPNA6 (99% identical), rat Kpna6 (99% identical), mouse Kpna6 (99% identical), pig KPNA6 (99% identical), guinea pig KPNA6 (99% identical), chimpanzee KPNA6 (96% identical), tropical clawed frog kpna6 (90% identical), zebrafish kpna6 (89% identical), Drosophila melanogaster Kap-alpha1 (63% identical). Paralogues in human: KPNA5 (85% identical), KPNA1 (81% identical), KPNA2 (46% identical), KPNA4 (46% identical), KPNA3 (46% identical), KPNA7 (40% identical).
Diseases named in the same sentence as KPNA6 in open-access papers:
KPNA6 is named in the same sentence as 15 diseases in open-access papers, as found by Europe PMC text mining. Sharing a sentence is not in itself a finding about the gene and the disease. The quoted sentences say what the papers report.
breast carcinoma (2 papers, 2015 to 2025). "Here we report the mechanism by which BIG3 blocks the nuclear translocation of PHB2 via interactions with multiple karyopherin alpha (KPNA) proteins, including KPNA1, KPNA5, and KPNA6, in ERα-positive breast cancer cells." (PMID 26052702, 2015). "In breast cancers, however, BIG3 captures PHB2 through its KPNA (KPNA1, KPNA5, and KPNA6)-binding region(s), thereby inhibiting the E2-dependent suppressive ability of PHB2." (PMID 26052702, 2015). "We found that overexpressed PHB2 interacted with KPNA1, KPNA5, and KPNA6, thereby leading to the E2-dependent translocation of PHB2 into the nuclei of breast cancer cells." (PMID 26052702, 2015).
Infertility (2 papers, 2021 to 2024). "However, further investigations will need to be performed to identify all the cellular and molecular mechanisms involved in the complex phenotype of infertility observed in Kpna6-deficient mice." (PMID 34473250, 2021). "The infertility phenotype of Kpna6-deficient mice underlines the hypothesis that this protein has unique functions in spermatogenesis, and that other karyopherin α subtypes cannot compensate for its absence." (PMID 34473250, 2021). "We show that ablation of Kpna6 in male mice leads to infertility and has multiple cumulative effects on both germ cells and Sertoli cells." (PMID 34473250, 2021). "Such a phenotype has been observed in KPNA6 KO mice, where the translocation of the transcription factor BRWD1 and the expression of transition nuclear proteins and protamines was markedly reduced, which resulted in a total infertility and reduced sperm count < 3% compared to WT." (PMID 39423201, 2024).
hepatitis C virus infection (1 paper, 2019). A viral infection caused by the hepatitis C virus. "For example, KPNA6 mediates Kelch-like ECH-associated protein 1 (Keap1)/Nuclear factor erythroid 2–related factor 2 (Nrf2) signaling pathway, affecting IFNα antiviral response, oxidative stress, and autophagy during hepatitis C virus infection." (PMID 31717720, 2019).
male infertility (1 paper, 2021). The inability of the male to effect fertilization of an ovum after a specified period of unprotected intercourse. "By contrast, only a truncated non-functional Kpna6 was found in the Kpna6ΔIBB/ΔIBB testes, which resulted in male infertility, suggesting that Kpna6 is essential for male fertility." (PMID 34473250, 2021).
ZIKV infection (1 paper, 2026). "Here, we found that ZIKV infection led to the relocation of KPNA6 to the perinuclear region." (PMID 42159396, 2026).
infection (4 papers, 2011 to 2025). The state of being infected such as from the introduction of a foreign agent such as serum, vaccine, antigenic substance or organism. "aegypti that differs in vector competence for DENV revealed that importin-β1 is upregulated upon infection in a susceptible strain, and the knockdown of Karyopherin 6 (KPNA6 or importin α7) inhibits Zika replication in Vero cells, which is reversed when the levels of this importin are restored." (PMID 36839463, 2023). "To further assess the effect of overexpression of KPNA6 on the replication of influenza A virus, we infected 293T cells overexpressing KPNA6 with H1N1WSN virus (multiplicity of infection [MOI] = 0.001) and measured the NP content and virus titer in the cell supernatant over time." (PMID 35044222, 2022). "In addition, the expression levels of KPNB1, KPNA1, KPNA2, KPNA4, KPNA6, and KPNA7 changed with the infection time of the three strains while KPNA3 and KPNA5 did not change with the incubation time." (PMID 40687856, 2025).
cancer (3 papers, 2013 to 2022). A tumor composed of atypical neoplastic, often pleomorphic cells that invade other tissues. "Enriched pathways for upregulated miRNAs included: “Chemical carcinogenesis–receptor activation” (p-value = 0.018) associated with ESR1, FGF18, JAG1, KPNA6, PPARA genes; the pathway “Proteoglycans in cancer” (p-value = 0.089) associated with genes ESR1, FRS2, HIF1A, PDCD4." (PMID 36359024, 2022). "We validated the knockdown effect of each KPNA (KPNA1, KPNA5, and KPNA6) on the interactions between endogenous PHB2 and nuclear ERα in BIG3-depleted cancer cells." (PMID 26052702, 2015). "The results showed that the depletion of only BIG3 led to interactions between endogenous PHB2 released from BIG3 with nuclear ERα but that the depletion of BIG3 and KPNA1, KPNA5, and KPNA6 did not, indicating that PHB2 binding to nuclear ERα in cancer cells is KPNA-mediated." (PMID 26052702, 2015).
tumor (2 papers, 2023 to 2025). "Notably, the proteins captured by AC-NP included several frequently mutated proteins in MC38 tumor cells, such as Hnrnpf, Aatf, Copb2, and Kpna6 53,54." (PMID 40379691, 2025). "Finally, the genes ARID4B, GALNT3, and KPNA6 were identified as other possible candidate tumor biomarkers." (PMID 37761387, 2023).
KPNA6 also shares sentences with these, for which no sentence is quoted: viral infection (2 papers); Alzheimer disease (1); cerebral malaria (1); COVID-19 (1); epilepsy (1); nasopharyngeal carcinoma (1); non-small cell lung carcinoma (1).